EZH2 (enhancer of zeste 2 polycomb repressive complex 2 subunit)
Diseases named in the same sentence as EZH2 in open-access papers (continued):
Sharing a sentence is not in itself a finding about the gene and the disease.
cancer (continued). "The difference in expression of EZH2/H3K27me3 in ESCs and iPSCs (low level) in comparison with CSCs (high level) extends even to cancer systems." (PMID 29853899, 2018). "EZH2 inhibitors are widely applied in pre-clinical and clinical trials of various cancers due to the remarkable link of EZH2 dysregulation to oncogenesis in multiple tissue types." (PMID 30002791, 2018). "High levels of EZH2 and correlated H3K27me3 are closely related to the poor clinical outcome of cancers, including lower overall survival and disease-free survival." (PMID 30002791, 2018). "Increasing evidence that links EZH2 activity to cancer has recognized EZH2 as an improtant driver of cancer initiation, growth and progression." (PMID 30542123, 2018). "Within lung tumor samples, LAT1 and EZH2 were co-expressed in cancer cells that were more undifferentiated and highly proliferative compared with not being expressed in the adjacent stromal tissue." (PMID 30103560, 2018). "Given its specific activities, EZH2 can be considered as an interesting target in several types of cancer." (PMID 30510924, 2018). "Since drugs targeting cdk4 and EZH2 are entering clinical trials, we propose that they should be tested in the treatment of cancers that become resistant to first-line genotoxic therapies." (PMID 29415991, 2018). "Other microRNAs (e.g. miR-126, miR-138, miR-32, miR-506, miR-137) are also reported to directly target EZH2 in different types of cancer and displayed different functions." (PMID 29556394, 2018). "Expressing SV40 large T-antigen in normal lung epithelial cells causes them to become cancer cells, and this correlated with the upregulation of LAT1, CD98 and EZH2 protein." (PMID 30103560, 2018). "PcG family members, such as BMI, Mel-18, and EZH2, are integral constituents of the polycomb repressive complexes (PRCs) and have been known to regulate cancer stem cell (CSC) phenotype." (PMID 29422082, 2018). "Aberrant EZH2 expression in cancer cells can help them to modulate immune response and immunotherapy." (PMID 29556394, 2018). "EZH2 downregulates expression of tumor suppressor genes and upregulates oncogenes, promoting cancer cell survival, proliferation, epithelial to mesenchymal and invasion." (PMID 29556394, 2018). "Overactive mutants of the histone lysine methyltransferase subunit of PRC2, Ezh2, are found in various types of cancers." (PMID 29904056, 2018). "This particular histone marker reduces tumor suppressor genes, and is one mechanism by which EZH2 is postulated to promote cancer progression." (PMID 30103560, 2018). "Among the multiple target genes of miR-106a in cancer cells, ZBTB4 is a transcriptional repressor regulating EZH2, a factor associated with decreased survival among BC patients." (PMID 29557526, 2018). "Given the identified pivotal roles of Ezh2 in these two critical aspects of cancer biology, promotion of GC progression by activation of Ezh2 is conceivable." (PMID 29335012, 2018). "Together, these results indicate that pharmacological inhibition of EZH2 represents a novel therapeutic strategy for CARM1-expressing cancers." (PMID 29434212, 2018). "Evidence implicating EZH2 in oncogenesis exists in a variety of cancer types including prostate, breast cancer, melanoma, and bladder cancer." (PMID 29988316, 2018). "In this review, we aim to discuss the molecular functions of EZH2, highlight recent findings regarding the physiological functions and related regulation of EZH2 in cancer pathogenesis." (PMID 29556394, 2018). "Ezh2 inhibitors are sometimes used as anti-cancer drugs and pharmacological inhibition of Ezh2 in the murine germ line resulted in depletion of H3K27me3." (PMID 29985950, 2018). "As various functions of EZH2 were discovered, it has become understandable that EZH2 plays critical roles in the development and progression of various cancers." (PMID 29556394, 2018).
cancer (continued). "Obviously, the development of these inhibitors is limited to those cancers in which there is a gain of function of EZH2." (PMID 30510924, 2018). "While CDK-mediated EZH2 phosphorylation is critical for cancer-cell invasion and osteogenic differentiation of mesenchymal stem cells, further investigation is needed toreveal the role of this interaction in the fate and function of cancer cells." (PMID 29556394, 2018). "SWI/SNF complexes are mutated in ~20% across human cancers and dependency of SWI/SNF-deficient tumors on EZH2 has been uncovered recently." (PMID 30138427, 2018). "Despite evidence that EZH2 is expressed in the cytoplasm of human malignancies, the function, mechanism, and consequences to cancer progression have remained unexplored." (PMID 30022044, 2018). "When PARPi is used, alkylating DNA damage-induced EZH2 downregulation would be disturbed, and EZH2-mediated gene silencing and cancer stem cell property are enhanced, leading to decreased sensitivity of PARPi." (PMID 29556394, 2018). "Stable cancer cells for differential EZH2 expression were achieved by retroviral transduction of particular plasmids (wild type, knockdown and EZH2 mutant constructs)." (PMID 29460395, 2018). "The expression of EZH2 is upregulated in many carcinomas, with the high level of EZH2 correlated with poor outcome of human tumors." (PMID 30064416, 2018). "In summary, in addition to cancer biology, EZH2 was, for the first time, proposed as a central player in Pb-induced neurotoxicity in this study." (PMID 29156711, 2017). "As an important epigenetic regulator, EZH2 is widely expressed in a number of human cancers and regulates the expression of target genes involved in proliferation, differentiation, and neoplastic cell transformation." (PMID 28548932, 2017). "A recent paper from the Liang group, demonstrated that Snail expression in cancer cells is able to upregulate EZH2 by inhibiting miR101 expression." (PMID 28195240, 2017). "Our results add Nr2e3 and Ezh2 to the recently identified regulatory interplay between Jag1 and 17beta-estradiol that is important in cancer and other tissue specific disorders including retinal diseases." (PMID 28386079, 2017). "EZH2 has been the subject of intense research in recent years due to its role in a wide range of cancers and to its potential as a therapeutic target." (PMID 28678185, 2017). "Enhancer of Zeste 2 Polycomb Repressive complex subunit 2 (EZH2), which has been shown to induce resistance and cancer cell migration and invasion was markedly down-regulated in MiaPaCa-GTR and MiaPaCa-GR cells." (PMID 28881737, 2017). "In particular, increased miR-101 or miR-138 leading to reduced EZH2 expression have been reported for various types of cancer including BC." (PMID 28060766, 2017). "Mutations and high expression of EZH2 have been observed in a variety of cancer malignancies, and is correlative with the poor prognosis in different human cancers, indicating the involvement of EZH2 in the development and progression of cancers." (PMID 28561778, 2017). "The results from our studies establish that Akt-mediated Ezh2 phosphorylation as a critical target for optimizing the expansion and quality of therapeutic T cells used for treating cancer and chronic infections." (PMID 29242551, 2017). "It is also clinically relevant in epigenetic cancer therapy and therefore many small molecule inhibitors have been developed that can specifically suppress the enzymatic activity of EZH2." (PMID 28410242, 2017). "SET- and MYND-domain containing protein 3 (SMYD3) is EZH2 target, and H3K4 methyltransferase plays a critical role in various human cancers by activating oncogenes and genes associated with cell-cycle regulation." (PMID 28740569, 2017). "The purpose of this study was to examine the expression levels of EZH2 in 96 pairs of primary cancer tissues and metastatic lesions obtained from patients with MBC." (PMID 28241804, 2017).
cancer (continued). "EZH2 regulates expression of the downstream genes, and then affects several physiological functions, including cancer progression, malignancy, and drugs resistance." (PMID 28561778, 2017). "To evaluate SmEZH2 as a possible new anti-parasite epigenetic target, we tested GSK343, a compound identified in human cancer cells as a highly potent, selective EZH2 inhibitor." (PMID 28406899, 2017). "EZH2 was first observed in cancer when it was identified as one of the most elevated genes in metastatic PCa and closely correlated with poor prognosis." (PMID 29141691, 2017). "In contrast to observations in other cancers, sensitivity to pharmacologic inhibition of EZH2 by GSK126 was decreased in the setting of reduced BAP1 expression." (PMID 28122578, 2017). "We surveyed the cancer genomic data of EZH2 in The Cancer Genome Atlas (TCGA) data base by using the cBioPortal platform." (PMID 28561778, 2017). "The enhancer of zeste homolog 2 (EZH2) is a core subunit of the polycomb repressor complex 2 (PRC2), which is overexpressed in numerous cancers and mutated in several others." (PMID 28410242, 2017). "Growing evidence demonstrates that EZH2 is imperative for cancer initiation, development, progression, metastasis, and drug resistance." (PMID 29202777, 2017). "This compound can also inhibit H3K27me3 in various cancer cells harboring wild-type, tyrosine Y641- or alanine A677-mutant EZH2 in a dose-dependent manner." (PMID 28415635, 2017). "Work from Ciechanover lab recently showed that PJA1 targets the main PRC2 components, including EZH2, to proteasome-mediated degradation in cancer cells." (PMID 28067271, 2017). "Linc-POU3F3 is increased in ESCC tissues and contributes to development of cancer through interactions with EZH2 to promote methylation of POU3F3." (PMID 28404901, 2017). "miR-101’s aberrant expression, namely its downregulation, has been involved in multiple cancers and has shown to mediate the overexpression of EZH2." (PMID 28143553, 2017). "As a significant epigenetic regulator, EZH2 is highly expressed in a wide range of human cancers and mediates the expression of target genes responsible for cell cycle progression, proliferation, differentiation, and neoplastic cell transformation." (PMID 27903964, 2017). "Enhancer of Zeste Homolog 2 (EZH2), a histone methyltransferase, has been found to play pivotal roles in the development of various cancers." (PMID 28679390, 2017). "Enhancer of zeste homolog 2 (EZH2) has been widely studied in the area of cancer epigenetics in recent years." (PMID 29141691, 2017). "EZH2 is also involved in regulation of cell cycle progression and dysregulation of EZH2 accelerates cell proliferation, resulting in cancer development." (PMID 28561778, 2017). "Significantly increased levels of UHRF1BP, c-Myc and EZH2 were also observed in cancer samples compared to normal lung." (PMID 28634396, 2017). "In fact, several DOT1 like histone H3K79 methyltransferase (DOT1L) and EZH2 inhibitors have progressed to being tested in clinical trials as cancer interventions." (PMID 28148257, 2017). "Here, we review up-to-date information regarding EZH2 expression patterns, functions, and molecular mechanisms in cancer stem cells in various malignant tumors and discuss the therapeutic potential of targeting EZH2 in tumors." (PMID 28415635, 2017). "Enhancer of zeste homolog 2 (EZH2) was the most significantly enriched TF overlapping CpGs with higher methylation in the cancer tissues from our dataset (Fisher’s Exact Test, Bonferroni adj." (PMID 28412973, 2017). "In cancer cells, Akt phosphorylates Ezh2 at serine 21 (pEzh2S21), thereby suppressing Ezh2 enzymatic activity." (PMID 29242551, 2017). "Several PcG proteins such as EZH2 and Bmi1 have been found to play important roles in cancer development and progression, including PCa." (PMID 28029659, 2017).
cancer (continued). "It has been reported that EZH2 promotes the cancer cell proliferation via suppressing the expression level of the cell cycle protein including p21 and p27." (PMID 28679390, 2017). "EZH2 inhibitors have shown promises in cancer clinical trials and become additional strategies to combat cancer and fibrosis." (PMID 28754964, 2017). "EZH2 is an oncogene that is upregulated in human epithelial-type cancers such as NSCLC and whose expression is inhibited by let-7/miR-98 family members, along with that of c-Myc, high mobility group AT-hook 2, and LIN28." (PMID 28587210, 2017). "Given the well documented roles of Snail and EZH2 as modulators of cancer stemness, we evaluated their potential role in eHsp90-mediated cellular plasticity." (PMID 28038472, 2017). "Our results support the potential clinical use of GSK343 for targeting EZH2 in EC and other human cancers." (PMID 28088786, 2017). "The successful implementation of molecularly targeted therapies against EZH2 requires a greater understanding of the potential mechanisms by which EZH2 contributes to cancer." (PMID 28678185, 2017). "Recent data have been shown that EZH2 is a critical oncogene via the repression of tumor suppressor genes in human cancers." (PMID 29221202, 2017). "Overexpression of EZH2 has been found in various cancers of the breast, lung, prostate and haematological malignancies, and is associated with poor disease prognosis." (PMID 28148257, 2017). "The links of EZH2 and DNMT1, the two epigenetic regulators and oncogenes, have been shown to be associated with tumorigenesis and cancer progression in several other studies." (PMID 28360411, 2017). "Elevated activity of EZH2 in cancer can be targeted by small-molecule drugs (e.g., GSK126, PubChem CID 68210102) and is associated with sensitivity to apoptotic cell death." (PMID 28265786, 2017). "In contrast, for those exhibiting consistent hypomethylation/overexpression in cancer, their expression across tumors is more likely to be consistently positively correlated with EZH2 or DNMT1 (or both)." (PMID 27899617, 2017). "For instance, polycomb directs de novo DNA methylation in cancer cells with enhancer of zeste homolog 2 (EZH2) serving as a recruitment platform for DNA methyltransferases as a possible mechanism." (PMID 31867127, 2017). "Enhancer of zeste homolog 2 (EZH2) is often increased in malignant tumors and is involved in metastasis." (PMID 28620234, 2017). "Key RNA-binding residues are spread out along the surface of EZH2, with other subunits including EED also contributing, and missense mutations of some of these residues have been found in cancer patients." (PMID 29185984, 2017). "EZH2 proves to be a good therapeutic target in MYC-positive cancers; however, DZNeP lacks the needed specificity to be a promising strategy in clinical applications." (PMID 28505071, 2017). "Further experiments have revealed that FOXF1-AS1 physically associates with the PRC2 component, EZH2 (enhancer of zeste 2 polycomb repressive complex 2 subunit), and its knockdown mediates metastasis and stemness of cancer cells in the EZH2-dependent manner." (PMID 28872613, 2017). "Another TSG target of EZH2 in multiple cancers is the E-cadherin gene (CHD1), the downregulation of which is critical for epithelial-mesenchymal transition (EMT) and metastasis." (PMID 28758948, 2017). "Dysregulation of EZH2-catalyzed H3K27 trimethylation is frequently observed in many types of cancers." (PMID 28418882, 2017). "There was significant overlap; 8/14 genes involved in OGID were somatically mutated in a diverse range of cancers (NSD1, EZH2, DNMT3A, PTEN, CHD8, HIST1H1E, MTOR, PIK3CA; p = 1.7 × 10−14)." (PMID 28475857, 2017). "Regulative correlations of EZH2 and miR-101 have been well documented in several human cancers and overexpressed EZH2 predicts poor prognosis of ESCC patients." (PMID 29100288, 2017).
cancer (continued). "Together, the evidence to date suggests that inhibition of EZH2 suppresses the functions of STAT3 signals involved in CSC maintenance, supporting that EZH2 can be regarded as a target for cancer therapy." (PMID 28415635, 2017). "In summary, the development of EZH2 inhibitors for cancer therapy is in early stages and there have been reports of resistance that need to be addressed." (PMID 28410242, 2017). "Due to the potential roles of EZH2 in cancer progression and malignancy, EZH2 has been considered as a relevant therapeutic target for cancers." (PMID 28561778, 2017). "A recurring histone modifier in cancer literature is the methyltransferase EZH2, a catalytic subunit within the polycomb repressive protein complex 2 (PRC2)." (PMID 28143553, 2017). "An unexpected finding was that, in addition to inducing EZH2 expression in cancer cells, MUC1-C was detectable in complexes with EZH2 on the CDH1 and BRCA1 promoters, invoking the notion that MUC1-C associates with EZH2." (PMID 28785086, 2017). "Another interesting chemokine ligand is CXCL14, which we observed to be hypermethylated and underexpressed in two cancer types (breast and colon), but which exhibited a distinctive anti-correlative expression pattern with EZH2/DNMT1 in most cancer types." (PMID 27899617, 2017). "The H3K27 methylase EZH2 is up-regulated in HCC tissue and is associated with cancer progression, invasion and proliferation." (PMID 29079534, 2017). "It has been reported that overexpression of EZH2 promoted cancer cell proliferation via downregulation of tumor suppressors p21 and p27." (PMID 28679390, 2017). "This antagonistic effect is incomplete because MYCN as a transcription factor does not only regulate the EZH2 transcription, but also regulates other cancer-related genes." (PMID 29022893, 2017). "Accumulating evidence demonstrates the potential of EZH2 expression for the development of anti-cancer therapeutics." (PMID 28418882, 2017). "Despite this evidence, the link between EZH2 and CSCs has been questioned by recent work comparing EZH2 expression in differentiated cancer cells and CSCs." (PMID 28415635, 2017). "Some reports have demonstrated that repression of EZH2 level by miRNAs results in inhibition of cancer metastasis." (PMID 28561778, 2017). "Previous studies have showed that EZH2 was overexpressed in a variety of human cancers, which enhanced tumorigenesis through various signaling pathways." (PMID 28679390, 2017). "Given the elevated expression of EZH2 in aggressive HPV-positive OPSCC phenotypes as well as other metastatic cancers, EZH2 and its related pathways remain an attractive target for chemotherapeutic agents." (PMID 28878842, 2017). "In agreement with previous studies showing that numerous miRNAs are silenced by EZH2 in human cancer cells, in EC cells, EZH2 mediated suppression of let-7b and miR-361, both of which inhibit EC cell proliferation, invasion and self-renewal." (PMID 28088786, 2017). "We have found that a variety of studies investigated the prognostic significance of EZH2 in diverse cancer types by meta-analysis." (PMID 27880940, 2017). "EZH2 is normally expressed in actively dividing cells and plays a critical role in cancer initiation, progression, and metastasis." (PMID 28740569, 2017). "Here, we demonstrate that targeting MUC1-C in diverse human carcinoma cells downregulates EZH2 and other PRC2 components." (PMID 28785086, 2017). "Pathologic activation of EZH2 by genetic alterations has been documented in various cancers, including hematological tumors, making EZH2 a potential therapeutic target." (PMID 26755663, 2016). "Numerous recent studies have concluded that EZH2 inhibition increases the sensitivity of cancer cells to radiation and traditional chemotherapy." (PMID 27793053, 2016). "Accumulated evidence indicates that EZH2 contributes to various aspects of cancer by regulating a variety of target genes." (PMID 26683709, 2016).